BRAF (B-Raf proto-oncogene, serine/threonine kinase)
Diseases named in the same sentence as BRAF in open-access papers (continued):
Sharing a sentence is not in itself a finding about the gene and the disease.
melanoma (continued). "BRAF mutations are found in the genes of about half of melanoma patients, with younger patients making up the majority." (PMID 33031392, 2020). "In this context, BRAF inhibitors (BRAFi) have generated remarkable clinical responses in a high proportion of melanoma patients harbouring V600BRAF mutations." (PMID 32098410, 2020). "In inhibitor-resistant melanoma cells with the BRAF mutation, platelet derived growth factor receptor (PDGFRbeta) overexpression is observed, but other changes are also present." (PMID 32605090, 2020). "In this study we focus on the biophysical and biological characterization of these particles encapsulating miR-204-5p and miR-199b-5p for their therapeutic potential in the treatment of BRAF-mutated melanoma." (PMID 32178301, 2020). "Vemurafenib is a competitive inhibitor of BRAF kinase activity, and especially inhibits melanoma with a V600 mutation." (PMID 32962182, 2020). "In any case, the results clearly indicated that Dnmt3b is a pro-tumorigenic protein in melanoma and necessary for melanoma formation in the context of BRAF mutation and loss of phosphatase and tensin homolog (PTEN)." (PMID 33024276, 2020). "Epidemiologically, BRAF-mutated melanomas occur in younger patients and very frequently display a superficial diffusion or nodular morphology." (PMID 33260892, 2020). "For oncogene-addicted cancers, such as BRAF+ melanoma, the presence of BRAF V600E or V600K mutation represents an effective predictive tool for the choice of specific target therapies." (PMID 33233603, 2020). "The major advantage of such combined treatments is the capacity to induce an accelerated tumor regression in most of the patients with BRAF V600 mutation-positive melanoma." (PMID 31979325, 2020). "In Japan, dabrafenib monotherapy and combination therapy of dabrafenib and trametinib were approved for use in the treatment of patients with BRAF mutation–positive unresectable malignant melanoma in March 2016." (PMID 32699976, 2020). "The presence of BRAF or NRAS mutations increases the risk of central nervous system (CNS) metastases in patients with advanced melanoma." (PMID 33282420, 2020). "We believe that NOS- and NOX-mediated promotion of pheomelanogenesis is a pre-requisite for melanoma initiation from dysplastic nevi with BRAF/NRAS mutational background." (PMID 32850409, 2020). "Constitutive activation of BRAF kinase through mutations is the most common way for melanoma to activate the MAPK pathway." (PMID 32714859, 2020). "Based on these results, we posit that DDRs are promising therapeutic targets in BRAF-mutated melanomas." (PMID 33014862, 2020). "The acknowledged mutated genes in human melanoma are BRAF and NRAS, as well as the newly discovered PPP6C, RAC1, SNX31, TACC1, STK19, and ARID28." (PMID 32286411, 2020). "Approximately 50% of melanoma patients harbor a BRAF, particularly V600E, mutation in tumors, which leads to increased expression of downstream effectors, favoring tumor survival." (PMID 33396632, 2020). "In accordance, a recent study demonstrated that the level of COX-2 expression highly influences the metastatic ability of human melanoma cells independently of the presence of NRAS or BRAF mutations." (PMID 33121001, 2020). "For example, B-Raf proto-oncogene (BRAF) gain of function mutation (BRAF V600E) contributes to immune escape of melanoma cells." (PMID 33344447, 2020). "A case report of cutaneous melanoma metastases sampled over time revealed a MAP2K1 (F53Y) missense mutation paired with a BRAF fusion." (PMID 32483240, 2020). "On univariate analysis, the diagnosis-specific Graded Prognostic Assessment including the BRAF status (Melanoma-molGPA) was associated with a significantly improved LC." (PMID 32059731, 2020). "Nearly all melanoma patients with a BRAF‐activating mutation will develop resistance after an initial clinical benefit from BRAF inhibition (BRAFi)." (PMID 31833658, 2020).
melanoma (continued). "A common oncogenic variant of BRAF (BRAFV600E) in melanomas potently activates the RAS/BRAF/MEK/ERK (MAPK) pathway, which promotes tumor immune editing, the expression of immunosuppressive cytokines and checkpoint markers, and reduces CTL infiltration." (PMID 35310881, 2020). "As shown by Parmenter and colleagues, CCL20 expression was significantly downregulated in a panel of oncogenic BRAF(V600) mutation-harbouring melanoma cell lines in response to treatment with the BRAF inhibitor vemurafenib." (PMID 32601464, 2020). "There are studies showing that antioxidants inhibit melanoma, as it was shown for the melanoma-inhibiting effect of antioxidant Fisetin, a plant polyphenol from the flavonoid group, during the treatment of BRAF-mutated human xenograft in mice." (PMID 33091721, 2020). "For instance, it has been shown that the increase of ctDNA level in the plasma of patients with BRAF-mutated melanoma treated with targeted therapies precedes the detection of relapses by imaging and by clinical evaluation." (PMID 32295074, 2020). "Common resistance mutations in melanoma are BRAF splice variants, BRAF amplification, neuroblastoma RAS viral oncogene homolog (NRAS) mutations and mitogen-activated protein kinase kinase 1/2 (MEK1/2) mutations." (PMID 33003483, 2020). "Another example is Vemurafenib, a drug widely used to treat tumors driven by pathogenic variants in the BRAF gene, e.g., melanoma or skin cancers." (PMID 32645997, 2020). "BRAF V600E mutation is observed in 40–50% of metastatic melanomas and drives constitutive activation of MAPK and ERK pathways." (PMID 32575838, 2020). "Mutations of RAS, RAF, and MEK were described in a large number of tumors: for example, RAS mutations have been found in about 1/3 of all human tumors and in 15–20% of melanomas, and BRAF is mutated in 8% of human tumors and in about 40–50% of melanomas." (PMID 32695793, 2020). "BRAF mutations and translocations have been described in melanocytic nevi, malignant melanoma, colon adenocarcinoma, glioblastoma and pilocytic astrocytoma and EGFR mutations, amplifications in lung adenocarcinoma and brain tumors." (PMID 31970428, 2020). "The emergence of BRAF splicing variants is a common mechanism of escape to BRAF inhibition in melanoma." (PMID 33216826, 2020). "Trametinib is an FDA-approved MEK inhibitor targeting advanced melanoma bearing BRAF V600E or V600K mutation with dabrafenib (BRAF inhibitor)." (PMID 32260561, 2020). "In BRAF-mutated melanoma, BRAF kinase becomes hyperactivated, resulting in increased cell proliferation and survival." (PMID 32645969, 2020). "We attempted to determine the mechanism through which phospho-ERK1/2 levels were elevated following the loss of HAT1 expression in BRAF-mutant melanoma cells." (PMID 32371878, 2020). "The most common is the V600E mutation which accounts for 80–90% of BRAF mutations in melanomas and is present in almost 60% of cutaneous cases but is present in only 5% of mucosal melanomas." (PMID 32645969, 2020). "The concomitant alteration of these genes correlates with the worst overall survival (OS) for melanoma patients harboring BRAF-mutations." (PMID 33202944, 2020). "In fact, more than half of melanoma patients (about 50–60%) harbor BRAF mutation, together with the corresponding downstream signal transduction in the MAPK (mitogen-activated protein kinase) pathway." (PMID 32731406, 2020). "In recent years, improved knowledge of melanoma pathogenesis has led to the development of BRAF and MEK inhibitors that target tumours carrying BRAF oncogenic mutations, accounting for 40%–50% of all melanoma cases." (PMID 33339135, 2020).
melanoma (continued). "Melanoma patients harboring mutated NRAS display different characteristics compared to those harboring mutated BRAF: they are older (>55 years) and have a story of UV exposure, thicker primary tumors and a higher rate of mitosis." (PMID 32850962, 2020). "Based on recent ESMO Clinical Practice Guidelines, BRAF mutation testing is mandatory in patients with resectable or unresectable stage III or stage IV melanoma and is highly recommended in high-risk resected disease stage IIC patients." (PMID 32695793, 2020). "BRAF mutations occur in more than 50% of melanoma, leading to gain of function of BRAF and thereby to the overactivation of the MEK-ERK signaling cascade." (PMID 32630674, 2020). "This form of therapy has been recently approved for the treatment of BRAF-mutated advanced melanoma." (PMID 33171792, 2020). "The identification of the mutations in the V600 codon of BRAF (35–50% of melanomas) and Q61 codons (less frequently, the G12 or G13 codon) of NRAS (10–25% of melanomas) prompted the era of target therapy." (PMID 33233603, 2020). "Of these three kinases, BRAF has the highest mutation rate and this has been reported to be up to 90% in melanoma tumours." (PMID 32645969, 2020). "Several studies found that a BRAF mutation in melanoma causes increased glycolysis but also attenuates OXPHOS." (PMID 33007949, 2020). "We first analyzed the baseline expression of PD‐L1 and the influence of vemurafenib on the expression of this molecule in three BRAF‐mutated human melanoma cell lines, A375, MEL5, and MEL28 using flow cytometry." (PMID 32330348, 2020). "Immunotherapy represents the only therapeutic option for wild-type melanomas and an alternative option for BRAF mutated melanoma." (PMID 33233603, 2020). "MiR-204-5p (together with miR-211-5p) was associated with resistance to a BRAF inhibitor in melanoma cells." (PMID 31947507, 2020). "The first actionable mutation to be targeted by specific drugs in melanoma, BRAF V600, was found in 2002 along several other drivers of human cancers." (PMID 32850962, 2020). "Pharmaceutical blocking of AMPK by compound C has been shown to remarkably reduce the RAFi-resistant clones arising from BRAF-mutated melanoma." (PMID 32807225, 2020). "Anti‐PD‐1 monotherapies (aPD‐1) are also associated with improved outcomes among patients with BRAF‐mutant melanoma." (PMID 32871054, 2020). "The B-Raf Proto-Oncogene, Serine/Threonine Kinase (BRAF) inhibitors, such as Sorafenib, are developed based on the trial of melanoma with the V600E mutation in BRAF6." (PMID 32103116, 2020). "Our analyses of TCGA data identified higher expression of BCL2 in cutaneous BRAF-WT melanoma, compared to those with a BRAF hotspot mutation." (PMID 32764384, 2020). "This is the first report describing prospectively analyzed, real-world data obtained from more than 100 Japanese patients with unresectable melanoma with BRAF mutation who received dabrafenib and trametinib." (PMID 32699976, 2020). "According to the results of Sanger sequencing and cell function tests, the edited BRAF V600E caused the apoptosis of melanoma cells." (PMID 33330635, 2020). "Melanoma cells carrying the mutated BRAF oncogene become addicted to its constitutive activity, which can be therapeutically targeted by kinase inhibitors, such as vemurafenib or its analog PLX-4720, achieving cytostatic and cytotoxic effects." (PMID 32784465, 2020). "For these reasons, we aimed to characterize the role of BRAF‐V600E mutation in modulation of PD‐L1 and Gal‐1 expression and to further investigate potential immunoregulatory properties of BRAF inhibitors in melanoma." (PMID 32330348, 2020). "NRAS mutations in melanoma tumors are responsible for the development of drug resistance in BRAF-mutated patients." (PMID 31906480, 2020). "The BRAF V600E mutant/PTEN-loss mouse experiment was conducted to determine the effect of HI-511 on melanoma development in mice." (PMID 32863956, 2020).
melanoma (continued). "The presence of ctDNA bearing BRAF mutation provided information regarding the responsiveness of malignant melanoma to targeted therapy that complements the usual tissue biopsy results." (PMID 33233603, 2020). "The iPLEX HS Melanoma panel (Agena Bioscience Inc., San Diego, CA) detects 97 clinically relevant variants in 11 melanoma relevant genes, including BRAF, at as low as 1% minor allele frequency from FFPE tissue." (PMID 32695793, 2020). "The majority of melanomas harbor point mutations of BRAF, NRAS, KIT, or NF1 that drive tumor growth." (PMID 32123303, 2020). "Here, we report that the BRAF-mutated melanoma, SKMEL5 cells can indeed repress both their glycolysis and OXPHOS activity when they transition into the idling state as a response to therapy." (PMID 32923395, 2020). "The BRAF p.V600E mutation has been found in several cancers, including melanoma, papillary thyroid carcinomas, colon cancer, gliomas, and papillary craniopharyngiomas." (PMID 33266265, 2020). "Similar increased antioxidant capacities after resistance development to MEK inhibitors have been reported in BRAF mutated melanoma cells." (PMID 32455924, 2020). "We also found a similar number of these mutations in our study, 75% of BRAF mutant melanomas carried the V600E mutation." (PMID 33282420, 2020). "Accordingly, BRAF mutations are associated with melanomas from anatomic locations with intermittent sun exposure, such as the trunk and extremities." (PMID 32429485, 2020). "Clinical trials on the association of antiangiogenic with immunotherapy or anti-BRAF/anti-MEK targeted therapy in advanced melanoma." (PMID 33193402, 2020). "The method has already been used to detect BRAF mutations in plasma samples of human patients with melanoma." (PMID 32330187, 2020). "In BRAF-mutated melanoma, the high expression of NAMPT is associated with targeted therapy resistance, and NAMPT is a therapeutic target for this subset of patients." (PMID 32005247, 2020). "In particular, the BRAF V600E mutation correlates highly with a poor prognosis and survival rate in melanoma patients." (PMID 32213878, 2020). "The identification and characterization of BRAF mutations led to the development of highly specific drugs which radically changed the therapeutic landscape of melanoma." (PMID 32760738, 2020). "In the setting of malignant melanoma, it has been shown that BRAF-inhibitor resistant melanoma harboring the BRAF V600E mutation activate oxidative phosphorylation as a means to escape from therapy." (PMID 32258244, 2020). "Many clinical reports evaluated the efficacy and safety of radiotherapy and BRAF inhibitors in melanoma BRAF V600 mutated patients." (PMID 32575838, 2020). "BRAF mutations occur quite often in melanomas, conferring to this kinase the ability to independently activate MEK, inducing its constitutive activation." (PMID 32695793, 2020). "BRAF mutation is present in almost half of melanoma patients and is responsible for tumoral proliferation in the absence of growth factors." (PMID 32167264, 2020). "On the other hand, treatment with BRAF inhibitors decreases the volume of enlarged BRAF-mutated melanoma cells in a glucose-dependent manner." (PMID 32295074, 2020). "Afterwards, as result of genome sequencing and identification of the main mutation, a series of therapeutic agents have been discovered; about half of all melanomas have mutations in the BRAF (v-raf murine sarcoma viral oncogene homolog B1) gene." (PMID 33050185, 2020). "We, therefore, analyzed the mTOR response using immunofluorescence in a different human melanoma cell line bearing the BRAF V600E mutation (G361)." (PMID 32531927, 2020). "Malignant melanoma (MM) is the most life‐threatening disease among all skin malignancies, and recent genome‐wide studies reported BRAF, RAS, and NF1 as the most frequently mutated driver genes." (PMID 32406600, 2020).
melanoma (continued). "Several meta-analyses have been performed to study KRAS and BRAF mutations in melanoma, non-small cell lung cancer (NSCLC), colorectal cancer and papillary thyroid cancer." (PMID 33680376, 2020). "Thirty-four percent (674/1978) of patients with melanoma were reported to have presented a correlation to melanomas located in the torso with mutation of the BRAF gene (OR = 1.41, 95% CI 1.21–1.63, P< 0.001)." (PMID 31274706, 2020). "It has long been known that BRAF mutation in melanoma cells confers them high glycolytic properties." (PMID 32455924, 2020). "Immunotherapy with anti-PD-1 agents is effective in adjuvant therapy for all high-risk melanoma patients while BRAF/MEK targeted therapy is effective for high-risk patients with BRAF mutation." (PMID 32894202, 2020). "In patients with a BRAF V600K mutation, the iORR was 6.7% (1 of 15 patients) in cohort A and 22.2% (4 of 18 patients) in cohort B. Among patients with BRAF V600E-mutated melanoma, the mPFS was about 16 weeks in both groups." (PMID 32575838, 2020). "In the BRIM-8 trial, patients diagnosed with stage IIC, IIIA, IIIB and IIIC BRAF-mutated melanoma were randomized to receive either vemurafenib or placebo." (PMID 32760738, 2020). "Trametinib is a reversible, highly selective, allosteric inhibitor of MEK1 and MEK2, which is FDA approved for melanoma, lung cancer, and anaplastic thyroid cancers with BRAF mutations." (PMID 32245042, 2020). "Similar to other types of solid tumors, melanoma shows frequent alterations in MAPK and PI3K/PTEN signaling pathways, especially with 40–60% of cultured primary melanoma cells bearing activating BRAF mutations." (PMID 32714859, 2020). "For example, inhibition of the protein kinase BRAF in melanomas with an activating mutation in the BRAF gene causes OXPHOS dependence via induction of PGC1α, a mitochondrial biogenesis regulator." (PMID 32397535, 2020). "Exposure of BRAF-mutated melanoma cells to inhibitors of the MAPK pathway enhanced stemness features by increasing the expression of YAP/TAZ and downstream genes, but not SCD1." (PMID 33202944, 2020). "Still, another approach in BRAF-mutated advanced-stage melanoma patients is a combination of TKIs and immunotherapies." (PMID 33260892, 2020). "The latest version of the National Comprehensive Cancer Network (NCCN) guidelines recommends BRAF inhibitors in combination with MEK inhibitors as a first-line treatment for unresectable melanoma with BRAF mutations." (PMID 32143442, 2020). "Kenting Water Mint EO has been identified as a chemopreventive agent against cutaneous side effects induced by vemurafenib, a BRAF inhibitor used for treatment of melanoma patients carrying the BRAFV600 mutation." (PMID 32948083, 2020). "The most prevalent mutation in melanoma is BRAF V600E, which constitutively activates downstream mitogen-activated protein kinase (MAPK) signalling." (PMID 33216826, 2020). "Taking melanoma caused by a BRAF gene mutation into consideration, the pharmacogenomics knowledge model covered 7 related drugs and 4846 triples were established in this case." (PMID 33084582, 2020). "BRAF-mutated (BRAF+) melanoma is characterized by specific clinical features, including more aggressive biological behavior than BRAF wild-type (WT) melanoma." (PMID 32605090, 2020). "In melanoma, the BRAF V600E gene mutation seems to be particularly interesting considering its presence is detected in about 40–50% of patients." (PMID 33171792, 2020). "To highlight the utility of our platform, we generated substitution mutations in each exon of three human genes (MAP2K1, KRAS, NRAS) associated with resistance to vemurafenib, which is a cancer drug targeting the BRAF V600E mutation in melanoma patients." (PMID 32242071, 2020). "NF1 gene encodes for neurofibromin, a protein that negatively regulates the MAPK pathway: it is the third most commonly mutated gene in melanoma, found in 46% of cases with BRAF and NRAS wild type, and often co-mutated with RAS-associated genes." (PMID 33233603, 2020).